ELOVL6 (ELOVL fatty acid elongase 6)
Diseases named in the same sentence as ELOVL6 in open-access papers (continued):
Sharing a sentence is not in itself a finding about the gene and the disease.
metabolic disease (10 papers, 2011 to 2026). A congenital disorder (due to inherited enzyme abnormality) or acquired (due to failure of a metabolically important organ) disorder resulting from an abnormal metabolic process. "Elongation of very long-chain fatty acids protein 6 (Elovl6) has been reported to be associated with clinical treatments of a variety of metabolic diseases." (PMID 32325903, 2020). "Previous studies have exhibited that the ELOVL6 was closely related to metabolic diseases and energy balance in mammal and fish, while few studies were reported in crustaceans." (PMID 37520818, 2023). "Blocking of 16:0‐to‐18:0 fatty‐acid elongation in mice by Elovl6 knockout was found to inhibit progression of metabolic disorders through alterations of fatty‐acid structures, i.e., increased 16:0 and decreased 18:0‐to‐24:0 levels." (PMID 32378734, 2020). "Elongation of very long-chain fatty acids protein 6 (Elovl6) is a crucial enzyme in the synthesis of endogenous fatty acids, which participates in the energy balance and metabolic diseases." (PMID 32050615, 2020). "A plenty of studies indicate that Elovl6 is an important inducible factor of many metabolic diseases." (PMID 32325903, 2020). "Recent studies have suggested that Elovl6 is related to energy balance and metabolic diseases, which could be regulated by nutrients and hormones." (PMID 32050615, 2020). "Thus, researchers have evaluated the therapeutic potential of ELOVL6 inhibitors for metabolic disorders." (PMID 22046322, 2011).
infection (5 papers, 2013 to 2025). The state of being infected such as from the introduction of a foreign agent such as serum, vaccine, antigenic substance or organism. "Meanwhile, after 2 days post-infection, Med17 overexpression (Med17-oe) led to the significant downregulation of adipogenesis-related genes, including Fasn, Scd1, Elovl6, and Lpin1 (p < 0.05)." (PMID 41199171, 2025). "As expected, silencing Mlxipl effectively down‐regulated the expression of its target genes including Fasn, Acaca, Elovl6, Scd1, Ptpn6 and Pnpla3 at 36 hours after Ad‐siMlxipl infection although their expression was restored to the control level at 72 hours." (PMID 31809000, 2020). "While ELOVL7 was activated already at 6 h of infection, both ELOVL4 and ELOVL6 displayed a delayed response (activated at 16 h of infection)." (PMID 28993767, 2017). "In Cpn group, infection induced down-regulation of acetyl-Coenzyme A acyltransferase 2 (Acaa2, FC = 0.41), ELOVL family member 6, elongation of long chain fatty acids (Elovl6, FC = 0.44), and nuclear receptor subfamily 1, group D, member 2 (Nr1d2, FC = 0.44)." (PMID 24131481, 2013).
neurodegenerative disease (1 paper, 2026). A disorder of the central nervous system characterized by gradual and progressive loss of neural tissue and neurologic function. "While its role in lipid metabolism is well established, recent studies have linked ELOVL6 to metabolic and neurodegenerative diseases, making it an attractive therapeutic target." (PMID 42246265, 2026).
ELOVL6 also shares sentences with these, for which no sentence is quoted: Hyperglycemia (4 papers); psoriasis (4); lymph node metastasis (2); autoimmune disease (1); brain cancer (1); Cachexia (1); cardiovascular disease (1); dwarfism (1); endometriosis (1); heart failure (1); hepatitis B (1); hepatitis C (1); Hypertension (1); ischemic stroke (1); leukemia (1); liver (1); lung squamous cell carcinoma (1); metastatic cancers (1); muscle atrophy (1); myocardial infarction (1); ovarian carcinoma (1); overnutrition (1); Parkinson disease (1); primary immunodeficiency (1); Thrombocytopenia (1); triple-negative breast carcinoma (1); uveal melanoma (1).